KLF11 (KLF transcription factor 11)
Description:
Transcription factor. Activates the epsilon- and gamma-globin gene promoters and, to a much lower degree, the beta-globin gene and represses promoters containing SP1-like binding inhibiting cell growth. Represses transcription of SMAD7 which enhances TGF-beta signaling (By similarity). Induces apoptosis (By similarity).
Synonyms: FKLF; TIEG2; Tieg3; MODY7; FKLF1
Tractability: PROTAC: ubiquitination databases record sites on it.
Gene: Protein-coding gene on chromosome 2 (10,042,849 to 10,054,836, forward strand). Ensembl gene ENSG00000172059.
Subcellular location: Nucleus
Subcellular location (Human Protein Atlas): Nucleoplasm; Cytosol; Focal adhesion sites; Nuclear bodies
Gene Ontology:
Molecular function: DNA-binding transcription factor activity, RNA polymerase II-specific; protein binding; sequence-specific double-stranded DNA binding; transcription cis-regulatory region binding; DNA-binding transcription factor activity; RNA polymerase II cis-regulatory region sequence-specific DNA binding
Biological process: negative regulation of cell population proliferation; negative regulation of transcription by RNA polymerase II; positive regulation of apoptotic process; regulation of G1/S transition of mitotic cell cycle; regulation of transcription by RNA polymerase II; cellular response to endothelin; negative regulation of DNA-templated transcription
Cellular component: nucleoplasm; chromatin; nucleus
Genetic constraint (gnomAD): Loss-of-function variants: 24 observed, 31.53 expected, observed/expected ratio (o/e) 0.76, 90% interval 0.55 to 1.07. The upper end of that interval is the gene's LOEUF score, 1.07, which puts it in group 4 of 6, group 1 being the genes least tolerant of losing a copy. Missense variants: 738 observed, 670.19 expected, observed/expected ratio (o/e) 1.1, 90% interval 1.04 to 1.17. Synonymous variants: 306 observed, 261.27 expected, observed/expected ratio (o/e) 1.17, 90% interval 1.07 to 1.29.
Gene-disease validity (ClinGen):
ClinGen rates the evidence that KLF11 causes each of these diseases.
monogenic diabetes (autosomal dominant): Refuted. Diabetes mellitus that is caused by mutations in a single gene.
Homologues: Orthologues: chimpanzee KLF11 (99% identical), macaque KLF11 (95% identical), dog KLF11 (79% identical), mouse Klf11 (75% identical), rat Klf11 (75% identical), pig KLF11 (71% identical), guinea pig KLF11 (58% identical), rabbit KLF11 (58% identical), tropical clawed frog klf11 (55% identical), zebrafish klf11b (43% identical), zebrafish klf11a (43% identical). Paralogues in human: KLF10 (34% identical), SP8 (22% identical), SP9 (20% identical), SP5 (19% identical), KLF13 (19% identical), KLF14 (19% identical), KLF12 (18% identical), SP7 (18% identical), KLF5 (18% identical), KLF15 (17% identical), KLF16 (17% identical), KLF8 (17% identical), and 10 more.
Diseases named in the same sentence as KLF11 in open-access papers:
KLF11 is named in the same sentence as 84 diseases in open-access papers, as found by Europe PMC text mining. Sharing a sentence is not in itself a finding about the gene and the disease. The quoted sentences say what the papers report.
diabetes (24 papers, 2012 to 2025). "Both KLF10 and KLF11 are closely linked to hepatic gluconeogenesis, hyperglycemia, glucose intolerance, diabetes, and hepatic metabolic disorders." (PMID 39272379, 2024). "Previous genetic studies have shown a significant association between KLF11 gene variants and diabetes." (PMID 39462409, 2024). "Krüppel-like factor 11 (KLF11), known for its missense mutations leading to the development of diabetes in humans, has also been identified as a novel protector of vascular homeostasis." (PMID 39462409, 2024). "Further studies, such as animal experiments, are needed to explain the association between altered KLF11 function and the diabetes pathogenesis and severity." (PMID 33604390, 2021). "The link between the KLF11 (c.1061G > T) variant and the putative diabetes pathophysiological process was assessed." (PMID 33604390, 2021). "In summary, our results indicate that the KLF11 (c.1061G > T) variant is associated with diabetes in this family." (PMID 33604390, 2021). "In human, alterations in KLF11 causes neonatal and juvenile Diabetes while its closely related gene, KLF14 causes obesity and adult type II diabetes." (PMID 24885560, 2014). "Mutations in the klf-11 locus are associated with risk of diabetes, while Klf-10 appears to negatively regulate lipogenic genes in hepatocytes." (PMID 23593032, 2013). "KLF11 is also a well-established human disease-associated gene that is etiologically implicated in severe variants of human diabetes, in several cancers as well as in the regulation of diverse endocrine/metabolic pathways." (PMID 23555910, 2013). "KLF11, a human disease-associated gene is etiologically implicated in diabetes, uterine fibroids and cancer." (PMID 23555910, 2013). "The current study provides mechanistic insights into how human diabetes-associated genetic mutations and variants that occur in these metabolic transcription factors, such as the KLF11 A347 variant, impair the regulation of metabolic gene networks." (PMID 23589285, 2013). "Like other diabetes-associated transcription factors, KLF11 regulates gene networks that are involved in metabolism that are also affected by the A347S variant." (PMID 23589285, 2013). "While MODY7 could not be confidently diagnosed in any of them, these cases are presented due to their rarity and the limited literature available on KLF11 variants in individuals with diabetes mellitus." (PMID 41153735, 2025). "These two diabetes-associated studies revealed the effects of a loss of KLF11 protein function." (PMID 33604390, 2021). "Moreover, previous studies demonstrated mutations of KLF11 p.Lys453del, KLF11 (p.I89L and p.G484S), and KLF11 (c.1061G>T) (Clinical and Functional Characteristics of a Novel KLF11 Cys354Phe Variant Involved in Maturity-Onset Diabetes of the Young) in Chinese population." (PMID 35921062, 2022). "KLF11 is expressed ubiquitously, with high expression levels in the pancreas and plays a key role in the regulation of pancreatic beta cell physiology, and its variants may contribute to the development of diabetes." (PMID 24586865, 2014). "However, recent data on the spectrum and prevalence of different KLF11 variants in patients with hyperglycemia suggest that it is premature to draw definitive conclusions regarding the limited role of this gene in the development of diabetes, including hereditary forms." (PMID 41153735, 2025). "KLF11 regulates glucose metabolism and insulin, with variations affecting pain sensitivity and diabetes." (PMID 40313396, 2025). "miR-10b-5p, which shares a seed sequence with miR-10a-5p, targets KLF11 and aids in glucose homeostasis, offering potential diabetes treatment." (PMID 38275797, 2024). "Human genetic studies have revealed an association between the gene polymorphisms of Krüppel-like factor 11 (KLF11), a member of the Sp1/KLF family of zinc finger transcription factors, and diabetes." (PMID 39462409, 2024).
diabetes (continued). "MODY is monogenic diabetes caused by a single gene mutation of either HNF-1α, HNF-1β, HNF-4α, HNF-1β, glucokinase, PAK4, KLF11, neurogenic differentiation 1 (neuroD1), and insulin (INS)." (PMID 35956399, 2022). "The combination of several studies allowed for an understanding of KLF11 function and diabetes outcome." (PMID 36361703, 2022). "Previous studies have shown that KLF11 is involved in the pathophysiological process of diabetes development." (PMID 33604390, 2021). "We excluded the remaining MODY genes (CEL, PDX1, PAX4, BLK, KLF11, NEUROD1) from this analysis since either very few missense mutations in these genes have been associated with early onset diabetes or the genetic evidence for association is limited." (PMID 29207974, 2017). "Interaction of KLF11 and WD40 protein Gβ2, for example, is disrupted in the presence of the A347S mutation, the variant associated with development of Maturity Onset Diabetes of the Young 7 (MODY7)." (PMID 24885560, 2014). "Alterations in KLF11, originally discovered by its role in growth regulation, causes juvenile (MODY7) and neonatal (Ins-331 mutation) diabetes." (PMID 24885560, 2014). "This has been the case for those genes within the KLF family of transcriptional regulators, such as KLF11 and KLF14, which have been strongly associated to diabetes, obesity, and insulin resistance/metabolic syndrome." (PMID 23589285, 2013). "In the current study, we demonstrate that the KLF11 TRD3 functions as a novel protein/protein interaction domain and that its function is altered in the A347S diabetes variant." (PMID 23589285, 2013). "In summary, we identified variants in BLK, CEL, KLF11, PDX1, and PAX4 that may contribute to various forms of diabetes, including rare MODY subtypes." (PMID 41153735, 2025). "Given the high frequency of KLF11 variants in the population, poor cosegregation with diabetes in the families, and a lack of enrichment of rare variants in a MODY cohort, the authors conclude that such variants were not disease-causing." (PMID 36361703, 2022). "However, the KLF11 variants do not demonstrate sex-based disparities in diabetes and cardiovascular phenotypes." (PMID 39462409, 2024). "miR‐10b‐5p targets KLF11, which in turn regulates KIT expression and improves GID in diabetes and post‐diabetes." (PMID 37218372, 2023). "The number of variants detected was greater than in Stage 1 since five additional monogenic diabetes genes (CEL, EIF2AK3, ABCC8, BLK, and KLF11) were sequenced." (PMID 29207974, 2017). "Although mutations in the KLF11 gene have been linked to maturity onset diabetes of the young type VII, KLF11 KO mice have decreased circulating insulin levels and increased insulin sensitivity, but do not develop overt diabetes." (PMID 35413089, 2022). "Notably, TFs linked to mature-onset diabetes of the young [MODY, HNF4A (MODY1), PDX1 (MODY4), and KLF11 (MODY7)] gain a significant number of target genes after 2 decades, which could explain how mutations in these genes can affect beta cell structure function to cause diabetes later in life." (PMID 36197983, 2022). "Notably, Klf11 null mice do not develop diabetes but still show decreased circulating insulin, abnormal glucose tolerance, and increased insulin sensitivity in peripheral organs." (PMID 39462409, 2024).
MODY (22 papers, 2012 to 2025). "Altered KLF11 function has been associated with maturity-onset diabetes of the young type 7 (MODY7) and neonatal diabetes; however, the precise molecular mechanisms remain incompletely understood." (PMID 41153735, 2025). "Mutations in human KLF11 may lead to the development of maturity-onset diabetes of the young 7 (MODY7)." (PMID 33604390, 2021). "KLF11 was proposed as a cause of MODY, with a candidate gene approach, in 2005 and a possible mechanism of action was suggested for the variants via the gain of function, which causes increased KLF11 repression activity." (PMID 36361703, 2022). "Moreover, mutations in human KLF11 may lead to the development of maturity-onset diabetes of the young 7 (MODY7)." (PMID 33604390, 2021). "To date, only a few studies identified mutations of KLF11 gene in screening MODY." (PMID 35921062, 2022). "However, the etiology of the MODY in our study demonstrated that variants of KLF11 genes were more frequently involved." (PMID 35921062, 2022). "Our findings align with those of a study of 224 MODY patients in Turkey, where mutations were identified in the following proportions: 65% in the GCK gene, 19% in HNF1A, 3.6% in HNF4A, 3.6% in KLF11, and 3.1% in HNF1B." (PMID 39859454, 2025). "We recently demonstrated that variants in BLK, KLF11, and PAX4 reported to cause MODY are common in the population, have limited co-segregation, and lack enrichment in MODY cases compared to controls." (PMID 40779032, 2025). "Of the 89 eDia3 patients, 10 (11.2%) carried likely pathogenic variants in genes (KLF11, GCK, ABCC8, PAX4, BLK and HNF1A) of MODY." (PMID 35921062, 2022). "In a Turkish cohort, KLF11-MODY accounted for 3.5% (n = 8) of MODY cases." (PMID 41153735, 2025). "Known MODY genes were not common causes of clinically suspected MODY, and KLF11 gene mutations were more frequently identified in these patients in China." (PMID 35921062, 2022). "KLF11-MODY is extremely rare and seemed to be more prevalent in Asian population." (PMID 35921062, 2022). "Findings from our study demonstrated that the mutations in KLF11 gene were not rare form of MODY in this Chinese cohort, with three novel heterozygous missense mutations (Gly172Arg for P-1; Glu265Lys for P-2; Gly251Glu for P-3)." (PMID 35921062, 2022). "However, KLF11, due to its role as a MODY gene, is a potential therapeutic target for adult-onset diabetes." (PMID 33604390, 2021). "To date, 14 disease genes for MODY are identified; most of them are transcription factors MODY1 (HNF4A), MODY3 (HNF1A), MODY4 (PDX1), MODY5 (HNF1B), MODY6 (NEUROD1/BETA2), MODY7 (KLF11), MODY8 (CEL), MODY9 (PAX4), MODY11 (BLK), and MODY14 (APPL1)." (PMID 31145732, 2019). "Own4 reported 16 genes associated with MODY, including BLK, PAX4, and KLF11, but their genetic evidence was not well documented." (PMID 38095268, 2024). "Laver et al5 also demonstrated by variant— and gene‐level genetic evidence that BLK, KLF11, or PAX4 was not a cause of MODY, and they proposed that these three genes should be removed from MODY diagnostic genetic testing." (PMID 38095268, 2024). "We did not include BLK, KLF11 and PAX4 in our gene panel due to lack of strong genetic evidence supporting the gene-disease association for MODY." (PMID 34789499, 2022). "However, some authors have argued that there is insufficient evidence to support a causal role for BLK, KLF11, or PAX4 variants in MODY pathogenesis, and these genes should not be routinely included in diagnostic testing." (PMID 41153735, 2025).
Type 2 diabetes (15 papers, 2008 to 2026). "We found that miR-10a/b-5p induces the growth of ICC and pancreatic β cells by targeting KLF11 (a causative gene for maturity-onset of diabetes of the young), which negatively regulates expression of KIT and insulin (INS) genes." (PMID 38396943, 2024). "In humans, amino acid changes in KLF11 are associated with maturity onset diabetes of the young type VII, whereas complete inactivation of this pathway by the -331-insulin mutation causes neonatal diabetes mellitus." (PMID 35413089, 2022). "Genetic analysis of KLF11 has revealed two rare variants (Ala347Ser and Thr220Met) that are segregated in families with early onset type 2 diabetes and significantly impair its transcriptional activity." (PMID 33604390, 2021). "Previous studies in human populations have demonstrated that defined changes in the sequence of the KLF11 protein (Q62R, T220M, and A347S) associate to early onset type II diabetes mellitus (OMIM MODY7)." (PMID 23589285, 2013). "We examined the contribution of KLF11 variants to the susceptibility to Type 2 diabetes in a Japanese population." (PMID 18199129, 2008). "In the light of the potential role of KLF11 in insulin action, we present a detailed re-examination of the KLF11 variants and test the possible association with Type 2 diabetes in 1818 Japanese participants." (PMID 18199129, 2008). "As the KLF11 gene is one of the key regulators in insulin secretion, we considered KLF11 to be an important candidate gene for Type 2 diabetes and systematically surveyed the genetic variants." (PMID 18199129, 2008). "Additionally, there was a heterozygous VUS in the KLF11 gene, linked to maturity-onset diabetes of the young type VII." (PMID 40870862, 2025). "As such, KLF11 is a valid candidate gene to determine the genetic predisposition to early onset and type 2 diabetes, as defects in this gene may lead to early onset or polygenic type 2 diabetes." (PMID 33604390, 2021). "Despite the strong evidences linking Krüppel-like factor 11 (KLF11) gene mutations to development of Type 2 diabetes, the precise physiological functions of KLF11 in vivo remain largely unknown." (PMID 24586865, 2014). "In conclusion, we were unable to find any association of common KLF11 variants with Type 2 diabetes in 1818 Japanese subjects, although a larger study may be required to completely exclude the potential effect of rare variants on this gene." (PMID 18199129, 2008). "KLF11 regulates expression of metabolic genes via an evolutionarily conserved protein interaction domain functionally disrupted in maturity onset diabetes of the young." (PMID 35413089, 2022). "Despite the strong evidences linking KLF11 to Type 2 diabetes development, the physiological functions of KLF11 in vivo remain largely unknown." (PMID 24586865, 2014). "Even after these two analyses, our data do not provide strong evidence that the KLF11 variant is associated with Type 2 diabetes in our Japanese population." (PMID 18199129, 2008). "Genetic variants in KLF11 are unlikely to have a major effect of Type 2 diabetes in the Japanese population, although they were significantly associated in North European populations." (PMID 18199129, 2008). "Furthermore, among the 18 KLF proteins, only KLF1, KLF6, and KLF11 have MIM phenotype numbers, associating them with dyserythropoietic anemia (613673), prostate (176807) and gastric (613659) cancers, and maturity-onset diabetes of the young, type VII (610508), respectively." (PMID 39202416, 2024). "Among the cognate genes, six including ALG8, DGKE, GNA12, KLF11, LRPAP1, and MMAB are related to multiple genetic diseases such as depressive disorder and Type-II diabetes." (PMID 22348086, 2012).